CRP (C-reactive protein)
Diseases named in the same sentence as CRP in open-access papers (continued):
Sharing a sentence is not in itself a finding about the gene and the disease.
hyperuricemia (115 papers, 2009 to 2026). An abnormally high level of uric acid. "Sedentary behavior increases hyperuricemia risk by elevating proinflammatory cytokines (IL-6, CRP, TNF-α) and reducing anti-inflammatory markers (IL-RA)." (PMID 41404102, 2025). "Data in the literature suggest that even asymptomatic hyperuricemia is associated with a proinflammatory status and increased levels of CRP, IL-6, and neutrophils." (PMID 40428204, 2025). "Previous studies have reported positive associations of CRP with uric acid concentration and hyperuricemia, which partially supports our findings." (PMID 39720251, 2024). "The association of hyperuricemia with higher CRP concentrations likely reflects its proinflammatory effect and has been reported in a large cohort of community-dwelling patients." (PMID 39271531, 2024). "It is observed that DTG-based and ATV/r-based ART are associated with hyperuricemia and increased high-sensitivity C-reactive protein levels, respectively." (PMID 39086939, 2024). "An additional interesting observation in our study is the association of hyperuricemia with male sex, as well as higher values of serum CRP and plasma NT-proBNP." (PMID 39271531, 2024). "In our present study, even after adjustment for nutrition and inflammation factors such as serum albumin, CRP, concentrations of creatinine, phosphorus and body mass index, hyperuricemia was still an independent predictor of all‐cause mortality." (PMID 34309202, 2021). "Thirdly, we further analyzed the comprehensive associations between high-sensitivity CRP and hyperuricemia in different subgroups according to sex, age, and BMI." (PMID 32565724, 2020). "Several previous studies had shown that CRP was positively associated with the prevalence of hyperuricemia or the high level of uric acid." (PMID 32565724, 2020). "The findings of this prospective cohort study suggested that higher level of high-sensitivity CRP is an independent risk factor for hyperuricemia in Chinese population, especially in women, while it is a limited indicator for prediction." (PMID 32565724, 2020). "The prevalence of metabolic syndrome (MetSy), its components, and other cardiometabolic risk markers such as hyperuricemia or elevated C-reactive protein levels differs between males and females." (PMID 32455627, 2020). "For example, one cross-sectional study of 1935 subjects suggested that high-sensitivity CRP is positively associated with the prevalence of hyperuricemia." (PMID 32565724, 2020). "Second, the large sample size in the present study (5,419 participants) allowed for sufficient statistical power to detect associations between high-sensitivity CRP and hyperuricemia." (PMID 32565724, 2020). "Participants with both hyperuricemia and systemic inflammation had the greatest mortality risk compared with those with both low serum urate and hs-CRP levels." (PMID 32295651, 2020). "Participants with both hyperuricemia and high systemic inflammation had the greatest mortality risk compared with those with low serum urate and low hs-CRP levels." (PMID 32295651, 2020). "The findings of this prospective cohort study suggest that higher level of high-sensitivity CRP is an independent risk factor for hyperuricemia in Chinese, especially in women." (PMID 32565724, 2020). "In the present study, we suggested that higher level of high-sensitivity CRP is an independent risk factor for hyperuricemia in Chinese women, while it is a limited indicator for prediction." (PMID 32565724, 2020). "High-sensitivity CRP was positively associated with the incidence of hyperuricemia after multivariate adjustments (P for trend = 0.04) in women." (PMID 32565724, 2020). "In the subgroup analyses, high-sensitivity CRP was positively associated with the incidence of hyperuricemia after multivariate adjustments (P for trend = 0.04) in women." (PMID 32565724, 2020).
hyperuricemia (continued). "Above all, it is the first study to examine the association between high-sensitivity CRP and the incidence of hyperuricemia by regarding high-sensitivity CRP as the primary exposure in Chinese population." (PMID 32565724, 2020). "Consistent with previous cross-sectional studies, we found that higher level of high-sensitivity CRP is an independent risk factor for hyperuricemia." (PMID 32565724, 2020). "The aim of the present cohort study was to explore the longitudinal association between high-sensitivity C-reactive protein (CRP) and hyperuricemia in Chinese population." (PMID 32565724, 2020). "In the subgroup analyses of the present study, we found that high-sensitivity CRP was positively associated with the incidence of hyperuricemia after multivariate adjustments (P for trend = 0.04) in women." (PMID 32565724, 2020). "No adequate data are available at this time for recommendations for CV screening solely based on non traditional risk factors in this group, i.e. hyperhomocys-teinemia, hyperuricemia, high calcium phosphorus product, high C reactive protein." (PMID 20676276, 2009). "Finally, although the CRP/HDL-c ratio was significantly associated with hyperuricemia in both males and females, we observed a stronger association in females (P for interaction = 0.031)." (PMID 40655403, 2025). "Besides, DR has been previously reported to be associated with some laboratory parameters, such as hyperuricemia, oxidative stress, inflammatory markers, microalbuminuria, serum creatinine (Cr), and C-reactive protein (CRP)." (PMID 38730329, 2024). "However, the design of previous studies has been limited in determining a causal association between high-sensitivity CRP and hyperuricemia." (PMID 32565724, 2020). "Another cohort study found that high-sensitivity CRP may serve as a candidate risk predictor for hyperuricemia in middle-aged South Korean men, while the association in the older and females has not been reported." (PMID 32565724, 2020). "Therefore, the aim of the present cohort study was to explore the longitudinal association between high-sensitivity CRP and hyperuricemia in Chinese population." (PMID 32565724, 2020). "Therefore, although CRP is a risk factor for hyperuricemia, its ability to predict hyperuricemia is limited." (PMID 32565724, 2020). "Participants with both hyperuricemia and high hs-CRP have elevated mortality risk." (PMID 32295651, 2020). "However, level of education, C-reactive protein, and hyperuricemia were negatively associated with CKD with DM." (PMID 29290951, 2017). "Hyperuricemia has been found associated with elevated CRP and other inflammatory markers and there might be link between uric acid and hs-CRP." (PMID 27006878, 2016). "Moreover, epidemiological studies have confirmed that children with high concentrations of CRP are more susceptible to hyperuricemia, and the serum uric acid concentration increased with rising CRP levels." (PMID 25356596, 2014). "Seong-Min Kim’s study showed that, compared to patients with paroxysmal supraventricular tachycardia, the AF group exhibits elevated TG and C-reactive protein levels, along with hyperuricemia." (PMID 41481639, 2026). "Further research is needed to directly compare its predictive performance against established markers like CRP in the context of hyperuricemia." (PMID 41450585, 2025). "A multi-cohort analysis reveals serum IL-1Ra levels correlate with both hyperuricemia severity and acute-phase C-reactive protein, suggesting its dual role as a disease activity biomarker and compensatory anti-inflammatory responder." (PMID 40388724, 2025). "When hyperuricemia occurs, CRP levels significantly increase, mostly as a result of tissue damage and associated inflammatory reactions." (PMID 39684678, 2024). "We first measured serum CRP and ICAM levels since hyperuricemia and inflammatory response are closely associated." (PMID 39684678, 2024).
hyperuricemia (continued). "The prevalence of hyperuricemia and high-sensitivity C-reactive protein levels ≥2 mg/L were 46.5% (40/86) and 24.4% (21/86) in the DTG group, and 30.2% (26/86) and 44.2 (38/86) in the ATV/r group, respectively." (PMID 39086939, 2024). "Taking dietary magnesium (Mg), for instance, is negatively correlated with C-reactive protein levels, while the latter is positively correlated with hyperuricemia." (PMID 38257085, 2024). "Vascular endothelial growth factor (VEGF), high-sensitivity C-reactive protein (hs-CRP), and cystatin C (Cys-C) have involvement in type 2 DR complicated with hyperuricemia (HUA) (HUDR), and we explored their clinical values in HUDR." (PMID 38075033, 2023). "The uric acid decline ratio and the inflammatory indexes (white blood cell count and C-reactive protein level) at the time of the attack were significantly higher in the normal uric acid level group than in the hyperuricemia group (P < 0.05)." (PMID 36683056, 2023). "This study showed that blood levels of inflammatory markers (WBC and CRP levels) were higher in the normal UA group patients than in hyperuricemia group patients during the perioperative acute gout attack." (PMID 36683056, 2023). "In the group with SUA < 420 μmol/L, CRP, changes in CRP and 24 h FEur in patients were higher, whereas SCr was lower than in the hyperuricemia group." (PMID 36896178, 2023). "Laboratory tests showed neutrophilic leucocytosis (16,700 cells/μl), profound hyperuricemia (12.3 mg/dl) and a raised C-reactive protein (CRP, 193 mg/l, normal range < 5)." (PMID 35611099, 2022). "Hyperuricemia is characterized by an increase in inflammation markers such as C-reactive protein (CRP), fibrosis markers such as galectin-3 (Gal-3) and carboxy-terminal telopeptide of type I collagen (CITP)." (PMID 35216477, 2022). "Hyperuricemia and an elevated high-sensitivity C-reactive protein level are often present in MetS, and they were both related to opioid purchasing in the present material." (PMID 33517898, 2021). "Compared with participants in the lowest tertile of high-sensitivity CRP, the multivariate-adjusted odds ratio (OR) (95% confidence interval [CI]) for incident hyperuricemia in the highest tertile was 1.36 (1.02, 1.82)." (PMID 32565724, 2020). "Education level, BMI, systolic and diastolic blood pressure, and hs-CRP levels were higher in the hyperuricemia group than in the non-hyperuricemia group for both sexes." (PMID 32560339, 2020). "As shown, the multivariate-adjusted ORs (95% CIs) in model 2 for hyperuricemia incidence across tertiles of high-sensitivity CRP were 1.00, 1.25 (0.94, 1.68), and 1.36 (1.02, 1.82), respectively." (PMID 32565724, 2020). "The optimal cut-off value of high-sensitivity CRP and AUC value for the detection of hyperuricemia were presented in the supplements." (PMID 32565724, 2020). "Another study reached a similar conclusion as the hyperuricemia patients had higher levels of CRP than the controls." (PMID 32565724, 2020). "Hyperuricemia participates in the production of many inflammatory mediators (such as interleukin, C-reactive protein, etc.)." (PMID 33304270, 2020). "When RDW is viewed as continuous variable, the relations of RDW and CRP to hyperuricemia were consistent with the previous results." (PMID 30290670, 2018). "Asymptomatic hyperuricemia is a pro-inflammatory condition affiliated with elevated levels of serum markers of inflammation, such as C-reactive protein, interleukin-6 and neutrophil count." (PMID 28523032, 2017). "The evidence is that hyperuricemia stimulated human vascular muscle cells proliferation and increased C-reactive protein expression in these cells." (PMID 24688543, 2014). "Fourth, to account for the possibility that an elevated CRP/HDL-c ratio may arise from distinct individual alterations in CRP or HDL-c, we examined their associations with hyperuricemia separately." (PMID 40655403, 2025).
hyperuricemia (continued). "Interestingly, the association between CRP/HDL-c and hyperuricemia was stronger in females than in males, with a significant interaction by gender." (PMID 40655403, 2025). "Importantly, our mediation analysis specifically identified systemic inflammation (measured by SII and CRP) as a significant pathway linking hyperuricemia to mortality." (PMID 40823312, 2025). "A laboratory examination showed a high erythrocyte sedimentation rate (ESR), high levels of C-reactive protein and hyperuricemia, and an imaging examination showed severe osteolytic destruction of the right shoulder glenoid and posterior humeral head subluxation." (PMID 33845812, 2021). "To explore whether there were interaction effects between sex, age, BMI, and high-sensitivity CRP on hyperuricemia, we performed subgroup analyses." (PMID 32565724, 2020). "However, the exact mechanism of the role of CRP in hyperuricemia and the differences between gender are still unclear." (PMID 32565724, 2020). "High-sensitivity C-reactive protein (CRP), as a general marker of both acute and low-grade chronic inflammation, its relationship to hyperuricemia may be bidirectional." (PMID 32565724, 2020). "However, hyperuricemia in the highest tertile group of high-sensitivity CRP was statistically significant compared with the lowest tertile group." (PMID 32565724, 2020). "Laboratory findings showed hyperuricemia and the C-reactive protein level was very high." (PMID 31521158, 2019). "As hyperuricemia was positively connected with CRP, uric acid may also have a role in inflammation and subsequent inflammatory related diseases." (PMID 29498657, 2018). "The biochemical assessment suggested downstream renal and electrolyte disturbances from exuberant light chain production with abnormalities including hyperuricemia, hypercalcemia, elevated lactate dehydrogenase, non nephrotic-range proteinuria and high level of C reactive protein." (PMID 30116534, 2018). "Both hyperuricemia and high levels of C-reactive protein contribute to CKD." (PMID 24663403, 2014). "In addition, many studies reported that hyperuricemia was associated positively with TNF-α, IL-6 and CRP, which suggested that uric acid may have a role in inflammation and subsequent inflammatory related diseases." (PMID 29498657, 2018). "Data from the RELAX study suggest that two-thirds of patients have a certain degree of hyperuricemia, more comorbidities, higher BNP levels, and higher C reactive protein levels." (PMID 34501474, 2021). "Moreover, the correlation between hyperuricemia and systemic inflammatory markers (such as C-reactive protein) and tumor necrosis was also explored, showing a further contribution to CV damage; use of ULT may lower, as expected, serum UA, decreasing the risk of CVD." (PMID 34733863, 2021). "However, as the most reliable marker for inflammation in the clinical practice, whether CRP is a cause of risk but not merely a symptom for hyperuricemia has an important preventive significance." (PMID 32565724, 2020). "Experimental studies have shown that hyperuricemia leads to elevated levels of agents of systemic inflammation such as interleukin 6 (IL-6), tumor necrosis factor a (TNF-a) and C-reactive protein (CRP)." (PMID 31815071, 2019). "Interleukin-6 (IL-6), tumor necrosis factor-alpha (TNF-α), and high sensitive C-reactive protein (hs-CRP) were also measured in order to determine the relationship of indices of inflammation with VAI and hyperuricemia." (PMID 29734946, 2018). "Research has confirmed that various inflammatory biomarkers—including high-sensitivity C-reactive protein (hs-CRP), systemic inflammatory response index (SIRI), and monocyte to high-density lipoprotein cholesterol ratio (MHR)—positively correlate with hyperuricemia." (PMID 41450585, 2025).
hyperuricemia (continued). "Compared with normouricemic group, RA patients with hyperuricemia were older (mean 58.3 years vs. 52.5 years), more male (47.8% vs. 18.0%), and having higher levels of ESR (median 49 mm/h vs. 35 mm/h) and CRP (median 12.85 mg/L vs. 5.41 mg/L), and higher HAQ-DI (median 0.75 vs. 0.38, all P < 0.05)." (PMID 36411486, 2022). "In our study, although the value of hs-CRP was not correlated with osteoporosis (p = 0.433), hyperuricemia was correlated inversely with osteoporosis (p = 0.013)." (PMID 33466908, 2021). "In the non-CKD group, individuals with hyperuricemia were younger and more physically active and had higher C-reactive protein levels than those without." (PMID 31836793, 2019). "Third, restricted cubic spline (RCS) modelling was employed to examine potential non-linear associations between CRP/HDL-C and hyperuricemia, and subgroup analyses were conducted to assess the robustness and consistency of the findings across different population subgroups." (PMID 40655403, 2025). "In addition, there were higher values of SBP, DBP, WC, BMI, TG, LDL, FBG, insulin, HOMA-IR, SCr, cystatin C, NAG, hs-CRP, IL-6, and RBP4 in the hyperuricemia group compared to the non-hyperuricemia group (P<0.05), but lower values of HDL, eGFR, and serum uric acid (P<0.001)." (PMID 35846279, 2022). "This could be a possible explanation for the results of an earlier study where CRP levels were not connected with hyperuricemia." (PMID 34246297, 2021). "However, the interaction effects between sex, age, BMI, and high-sensitivity CRP on hyperuricemia were nonsignificant." (PMID 32565724, 2020). "Patients with hyperuricemia more frequently received PZA at the start of TB treatment and exhibited higher hemoglobin levels and lower CRP levels than those without hyperuricemia." (PMID 37972037, 2023). "Finally, considering the economic feasibility of epidemiological study, traditional inflammation markers such as CRP, ferritin and interleukin 6, which could be used to compare the predictive power with MHR for hyperuricemia, were not collected in present study." (PMID 32178680, 2020).